RHOXF1P3 (Rhox homeobox family member 1 pseudogene 3)
Synonyms: XCP; lncRNA1456
Gene: Protein-coding gene on chromosome X (119,942,834 to 119,992,838, forward strand). Ensembl gene ENSG00000282933.
Diseases named in the same sentence as RHOXF1P3 in open-access papers:
RHOXF1P3 is named in the same sentence as 4 diseases in open-access papers, as found by Europe PMC text mining. Sharing a sentence is not in itself a finding about the gene and the disease. The quoted sentences say what the papers report.
breast tumors (1 paper, 2021). "We then analyzed the expression of RHOXF1P3 in a published RNA-seq dataset including 63 breast tumors and 10 adjacent normal tissues, which also showed upregulated expression of RHOXF1P3 in tumor samples." (PMID 33888849, 2021). "Together, our results demonstrated that pseudogene RHOXF1P3 is not only translated, but also upregulated in a subset of breast tumors." (PMID 33888849, 2021).
ovarian carcinoma (1 paper, 2021). A malignant neoplasm originating from the surface ovarian epithelium. "In addition, RHOXF1P3-encoded peptides were also detected in two ovarian cancer patients." (PMID 33888849, 2021). "The notable examples were RHOXF1P3 (Rhox homeobox family member 1 pseudogene 3) and MCTS2P (malignant T cell amplified sequence 2 pseudogenes) which were repeatedly detected from independent datasets of breast and ovarian cancers." (PMID 33888849, 2021).
tumor (2 papers, 2021 to 2022). "For instance, using cancer proteomics datasets, 1970 novel peptides of pseudogenes were found in tumor tissues, where some pseudogenes-encoded peptides are tumor-specific as pseudogene RHOXF1P3 is upregulated up to 16 folds in breast cancer." (PMID 35875144, 2022).
cancer (1 paper, 2021). A tumor composed of atypical neoplastic, often pleomorphic cells that invade other tissues. "They identify peptides from non-coding genes including DGCR9 and RHOXF1P3 that are upregulated in tumors compared to controls, suggesting that non-coding gene-encoded peptides may be a source of neoantigens in some cancers." (PMID 33888849, 2021).